SOCS1 (suppressor of cytokine signaling 1)
Diseases named in the same sentence as SOCS1 in open-access papers (continued):
Sharing a sentence is not in itself a finding about the gene and the disease.
influenza (12 papers, 2014 to 2024). An acute viral infection of the respiratory tract, occurring in isolated cases, in epidemics, or in pandemics; it is caused by serologically different strains of viruses (influenzaviruses) designated A, B, and C, has a 3-day incubation period, and usually lasts for 3 to 10 days. "Using gene-deficient and infectious animal models, we determined how SOCS1 regulates immune defense against influenza infection." (PMID 25500584, 2014). "However, we found these SOCS1-haplodeficient mice were susceptible to influenza infection similar to WT animals." (PMID 25500584, 2014). "This study presents evidence that miR19a/b, through targeting SOCS1, plays a role in mediating influenza-induced cytokine storms both in vitro and in vivo." (PMID 38435118, 2024). "Transfecting agomir-miR-19a/b into A549 cells resulted in a significant decrease in the expression of SOCS1 and influenza protein." (PMID 38435118, 2024). "Galectin-3 has been implicated in the regulation of suppressor of cytokine signaling 1 (SOCS1) and retinoic acid-inducible gene I (RIG-I) expression during influenza and Streptococcus pneumoniae co-infection." (PMID 37298569, 2023). "For instance, influenza infected patients had augmented mRNA level of the genes, with the exception of SOCS-1." (PMID 36298646, 2022). "SOCS1 is an ISG induced during influenza infection to inhibit the expression of IFNs and their downstream signaling by inhibiting STAT1 or JAK1, which are required for signaling via this pathway." (PMID 34691044, 2021). "These traits led to decreased viral loads and lung injury, and accordingly increased survival rates of SOCS1−/−IFN-γ−/− mice following influenza infection." (PMID 25500584, 2014). "We show that SOCS1 in innate/stromal cells is involved in aggravated lung injury, consistent with influenza-induced SOCS1 expression in both cell types." (PMID 25500584, 2014). "Of note, these frequencies were significantly increased in all influenza-infected mice at 11 dpi, particularly DbNP366-specific T cells in SOCS1−/−IFN-γ−/− animals." (PMID 25500584, 2014). "SOCS1 and SOCS3 expression has been associated with symptomatic influenza infection, whereas SOCS2 and SOCS5 have been linked to asymptomatic disease." (PMID 24809749, 2014). "Here we demonstrate that mice with a targeted mutation in both SOCS1 and IFN-γ displayed increased adaptive immune responses at the early stage and reduced inflammatory cell infiltration at the resolution stage of influenza infection." (PMID 25500584, 2014). "Although the role of IL-4 during influenza infection remains debatable, SOCS1−/−IFN-γ−/− mice showed increased IL-4 production following influenza infection." (PMID 25500584, 2014). "So far very little is known regarding the role of different SOCS proteins in influenza infection, outside of the ability of SOCS1 and SOCS3 to regulate specific cytokine receptor complexes." (PMID 24809749, 2014). "IAV infection upregulated SOCS1 and SOCS3, and SOCS1/3 antagonist peptide could protect mice against lethal influenza infection." (PMID 32532301, 2020). "Therefore, we propose that B-1 cell activity is increased in influenza–infected SOCS1−/−IFN-γ−/− mice, possibly due to enhanced type I IFN signaling." (PMID 25500584, 2014). "Therefore, we developed SOCS1−/−IFN-γ−/− mice to evaluate the role of SOCS1 during influenza infection." (PMID 25500584, 2014). "Therefore, as an alternative approach, we demonstrated that adoptive transfer of CD8+ T cells isolated from naïve SOCS1−/−IFN-γ−/− mice rescued RAG1−/− animals from lethal influenza infection." (PMID 25500584, 2014). "To determine how SOCS1 may exacerbate lung injury, we investigated its regulatory effect on influenza-induced inflammatory responses." (PMID 25500584, 2014).
influenza (continued). "Here we show that SOCS1−/−IFN-γ−/− mice exhibited significantly enhanced resistance to influenza infection, as evidenced by improved viral clearance, attenuated acute lung damage, and consequently increased survival rates compared to either IFN-γ−/− or WT animals." (PMID 25500584, 2014). "In contrast, several genes involved in the interferon-stimulated innate immune response (OAS1, OAS2, SOCS1, DDX58, 16 CXCL10) were upregulated following influenza superinfection during SARS-CoV-2 infection." (PMID 38178911, 2023). "To address the regulation of the IFN pathway by Tpl2 in response to influenza infection, we first measured the expression of both STAT1 and SOCS1, which serve as positive and negative regulators of the IFN pathway, respectively." (PMID 34691044, 2021). "SOCS1−/−IFN-γ−/− mice exhibited significantly decreased production of IL-6 and IL-10 at 7 dpi but increased IL-4, IL-5 and IL-13 levels in airways during influenza infection." (PMID 25500584, 2014). "Therefore, although SOCS1−/−IFN-γ−/− mice exhibited increased CD4+ T cell and influenza-specific antibody responses, these animals were competent in CD4+ T cell-independent resolution of influenza infection." (PMID 25500584, 2014). "Since it is well established that IFN-γ is dispensable for protection against influenza infection, we generated SOCS1−/−IFN-γ−/− mice to determine whether SOCS1 regulates antiviral immunity in vivo." (PMID 25500584, 2014). "The distinct and non-competing detrimental roles of SOCS1, as revealed in this study, make it an appealing target in the design of effective immunotherapies for combating influenza infection." (PMID 25500584, 2014). "Anti-CD8 antibody-treatment depleted CD8+ T cells in IFN-γ−/− mice; however, even with an increased dosage, it failed to adequately deplete CD8+ T cells in influenza-infected SOCS1−/−IFN-γ−/− mice." (PMID 25500584, 2014). "Conversely, anti-CD4 antibody treatment did not affect the severity of influenza-induced lung injury in either IFN-γ−/− or SOCS1−/−IFN-γ−/− mice." (PMID 25500584, 2014). "Surprisingly, despite their markedly reduced viral burdens, RAG1−/− mice reconstituted with SOCS1−/−IFN-γ−/− adaptive immune cells failed to ameliorate influenza-induced lung injury." (PMID 25500584, 2014). "The identification of these non-competing detrimental roles of SOCS1 could have important therapeutic implications for treating influenza infection." (PMID 25500584, 2014). "Therefore, reduced virus burden alone does not account for the ameliorated immunopathology in influenza-infected SOCS1−/−IFN-γ−/− mice." (PMID 25500584, 2014). "Furthermore, here we demonstrate that these non-competing detrimental effects on host resistance to influenza infection are mediated by SOCS1 expression in different cell types." (PMID 25500584, 2014).
liver fibrosis (12 papers, 2010 to 2025). "The loss of SOCS1, a key regulator of inflammatory cytokine and growth factor signaling in the liver, promotes liver fibrosis." (PMID 37860002, 2023). "We have shown that whole body SOCS1-deficient mice in an IFNγ-deficient background are highly susceptible to liver fibrosis induction following carbon tetrachloride (CCl4)-induced necro-inflammatory chemical injury." (PMID 37860002, 2023). "SOCS1 can regulate several cytokines and growth factors implicated in liver fibrosis." (PMID 37860002, 2023). "As SOCS1 was initially discovered as a negative regulator of the inflammatory cytokine IL-6 signaling, loss of SOCS1 could amplify IL-6 signaling and promote liver fibrosis." (PMID 37860002, 2023). "Yoshida and colleagues demonstrated the severity of liver fibrosis has strong relevance with SOCS1 gene methylation in 200 patients with chronic liver disease." (PMID 36594057, 2023). "We have also shown that selective ablation of SOCS1 in myeloid cells results in heightened sensitivity to liver fibrosis, indicating a key role of SOCS1 in regulating cytokine responses in macrophages during hepatic fibrogenic response." (PMID 37860002, 2023). "To directly assess the role of SOCS1 in regulating HSCs responses during liver fibrosis, we crossed Socs1fl/fl mice with LratCre deleter mice, which ablates floxed genes specifically in HSCs in the liver." (PMID 37860002, 2023). "Suppressor of cytokine signaling 1 (SOCS1) is a suppressor of liver fibrosis and hepatitis-induced tumorigenesis, and SOCS1 hypermethylation is more likely found in males (63%) than in females (41%)." (PMID 33917049, 2021). "Liver fibrosis is strongly correlated with SOCS1 gene silencing through DNA methylation, and this firmly supports that the inhibition of SOCS1 leads to the progression of autoimmune hepatitis in SLE." (PMID 29085365, 2017). "SOCS1 heterozygous mice exhibit enhanced liver damage, severe liver fibrosis, and increased mortality after the treatment with DMN, compared to wild type mice." (PMID 20862390, 2010). "Altered expression of these miRNA in macrophages (in a similar direction as we observed) has been implicated in lung and liver fibrosis via reduced STAT6 signaling; mir-142-5p targets SOCS1 (a negative regulator of STAT6 phosphorylation), and mir-130a-3p targets the PPAR-g inhibitor." (PMID 37344825, 2023). "As macrophages release many cytokines and growth factors that directly impact HSCs during liver fibrosis, we ablated the Socs1 gene selectively in HSCs using the Cre recombinase expressed under the promoter of lecithin retinol acyltransferase (LRAT) involved in retinol storage in HSCs." (PMID 37860002, 2023). "However, we have shown that primary HSCs from whole body SOCS1 deficient mice display increased proliferation to PDGF stimulation, suggesting a role for SOCS1 in regulating HSC proliferation in liver fibrosis." (PMID 37860002, 2023). "Diseased SOCS1+/− mice exhibited more severe liver fibrosis than wild-type littermates." (PMID 29085365, 2017). "For instance, SOCS1 in hepatocytes acts as a negative regulator, inhibiting CCL2 expression and subsequent monocyte infiltration to alleviate CCl4-induced hepatic fibrosis." (PMID 41479922, 2025). "Overall, our findings show that SOCS1 regulates HSC activation by TGFβ and thereby controls liver fibrosis and HCC development at least partly via attenuating pro-inflammatory macrophage recruitment and promoting their transition to restorative macrophages." (PMID 37860002, 2023).
liver fibrosis (continued). "Our findings indicate that (i) SOCS1 expression in HSCs is a critical to control liver fibrosis and development of hepatocaellular carcinoma, and (ii) attenuation of HSC activation by SOCS1 regulates pro-inflammatory macrophage recruitment and differentiation during liver fibrosis." (PMID 37860002, 2023). "In cattle, liver fibrosis has been proposed as a downstream effect of upregulated TNF and IL1B, which would activate the genes that were also upregulated in the bovine study, i.e., IL6, PLAU, SERPINE1, TNFRSF1A, SOCS1, and CTSB." (PMID 34616397, 2021). "Our findings reveal a non-redundant cell-intrinsic role of SOCS1 in HSCs that controls HSC activation by TGFβ and amplification of the hepatic inflammatory response in liver fibrosis." (PMID 37860002, 2023).
multiple sclerosis (12 papers, 2014 to 2025). A progressive autoimmune disorder affecting the central nervous system resulting in demyelination. "Single nucleotide polymorphisms in SOCS1 have been linked to multiple sclerosis (MS), and SOCS1 mimetics have shown efficacy in MS animal models." (PMID 41249727, 2025). "Moreover, SOCS1 polymorphisms have previously been associated with increased susceptibility to multiple sclerosis development and epigenetic variations of SOCS1 gene have been highlighted between MS patients and healthy individuals." (PMID 41249727, 2025). "In an included MS study, miR-155 was elevated in T cells from patients with active multiple sclerosis, which correlated with lower expression of the SOCS1 gene (a suppressor of cytokine signaling) and skewing toward a T_H17 phenotype." (PMID 41376628, 2025). "Although multiple sclerosis has not yet been associated with SOCS1 haploinsufficiency, SOCS1’s role as a regulator of inflammation has been described in murine models of MS." (PMID 41249727, 2025). "Previous studies have shown that multiple sclerosis-associated risk variants in CLEC16A act as expression quantitative trait loci for CLEC16A itself in human pancreatic β-cells, for DEXI and SOCS1 in thymic tissue samples, and for DEXI in monocytes and lymphoblastoid cell lines." (PMID 26203907, 2015). "Furthermore, SOCS1 regulates the differentiation of naive T cells into T helper 1 and T helper 17 subsets, which have been identified among the primary actors initiating the inflammatory process triggering multiple sclerosis and EAE, as well as relapses." (PMID 41249727, 2025). "In addition, we have previously demonstrated that a peptide mimic of the KIR region of SOCS1 (SOCS1-KIR) prolonged the survival of SOCS1−/− mice, ameliorated pathology in a rodent model of multiple sclerosis, and mitigated experimental rodent uveitis." (PMID 33737712, 2021). "Because this animal model of multiple sclerosis (MS) shares essential immunopathological features with EAU, we examined whether the suppression of EAU in rats treated with SOCS1-KIR derived in part from inhibiting expansion of inflammatory cells in the retina during EAU." (PMID 27703302, 2016).
Arthritis (11 papers, 2011 to 2025). Inflammation of a joint. "Identification of the SOCS1 variant led to initiate ruxolitinib 10 mg twice daily, which resulted in spectacular improvement of intestinal symptoms as well as of arthritis, enabling steroids withdrawn." (PMID 37156989, 2023). "In the present study, we used four independent cohorts of patients with arthritis to test for associations between SOCS1 expression and RA." (PMID 32670294, 2020). "We found that early events including up-regulation of SOCS1 and an increased proportion of Tregs associated with resistance to arthritis development." (PMID 27159398, 2016). "Lower baseline SOCS1 levels were associated with poorer disease control in response to methotrexate and other conventional synthetic disease-modifying anti-rheumatic drugs in early arthritis, and to rituximab in established (active) RA." (PMID 32670294, 2020). "Moreover, we identified several single nucleotide polymorphisms in the SOCS1 gene that correlated with SOCS1 mRNA expression, and that might identify those patients with early arthritis that fulfill RA classification criteria." (PMID 32670294, 2020). "In 2022, a patient with heterozygous SOCS1-deletion and severe enthesitis-related arthritis showed significant improvement upon tofacitinib treatment, even stabilizing immunocytopenia (ITP) that was poorly controlled with conventional immunosuppression." (PMID 38711523, 2024). "In a similar line, Stat1−/− mice show exacerbated zymosan-induced arthritis, possibly due to reduced SOCS1 expression." (PMID 32670294, 2020). "Using four independent cohorts of patients with arthritis, we characterized the correlation between SOCS1 mRNA levels and clinical outcome." (PMID 32670294, 2020). "Here we show that patients with early arthritis who are unable to upregulate SOCS1 expression are more likely to be classified as having RA and have a higher risk of not achieving remission and/or failing to respond to treatment." (PMID 32670294, 2020). "Similar results validate SOCS1 as a negative regulator of proinflammatory signaling in the methylated bovine serine albumin (mBSA)/IL-1-dependent model of arthritis in SOCS1−/− IFN-γ−/− mice." (PMID 26579124, 2015). "In fact, increased expression of both SOCS1 and 3 have been shown to decrease the severity of arthritis." (PMID 23166758, 2012). "To investigate the link between increased IL-10 production and suppression of arthritis we determined the mRNA levels of the suppressors of cytokine signalling 1 and 3 (SOCS1 and SOCS3)." (PMID 23166758, 2012). "However, studies directly assessing the therapeutic administration of peptidomimetics of SOCS1 in fully developed arthritis models remain limited." (PMID 41393140, 2025). "On the other, it may show that the immune system is trying to overcome the ongoing inflammatory process, as upregulated SOCS1 expression may have inhibitory effects on arthritis development." (PMID 33362761, 2020). "Thus, the early increase in Socs1 mRNA coincides with the increased frequency of Tregs and resistance to arthritis development." (PMID 27159398, 2016). "Of interest is the finding that SOCS1 is commonly targeted in all four diseases; fifthly, using IPA, we found that these diseases had active pathways in six categories: arthritis, cancer, development, immunology, metabolism, and proliferation/survival." (PMID 30369883, 2018). "Further, up-regulation of SOCS1 and/or 3 in CIA coincided with increased IL-10 production and reduced severity of arthritis." (PMID 27159398, 2016). "In addition, SOCS1 expression did not discriminate between patients in remission regarding pre-arthritis stages or treatment effects." (PMID 32670294, 2020).